SLC16A6 (solute carrier family 16 member 6)
Description:
Monocarboxylate transporter selective for taurine. May associate with BSG/CD147 or EMB/GP70 ancillary proteins to mediate facilitative efflux or influx of taurine across the plasma membrane. The transport is pH- and sodium-independent. Rather low-affinity, is likely effective for taurine transport in tissues where taurine is present at high concentrations.
Synonyms: MCT6; MCT7
Tractability: Antibody: its Gene Ontology location is reachable by antibodies, with high confidence; UniProt places it where antibodies can reach, with medium confidence; UniProt predicts a signal peptide or a membrane-spanning region. PROTAC: ubiquitination databases record sites on it.
Gene: Protein-coding gene on chromosome 17 (68,267,026 to 68,291,267, reverse strand). Ensembl gene ENSG00000108932.
Subcellular location: Basolateral cell membrane
Subcellular location (Human Protein Atlas): Vesicles
Gene Ontology:
Molecular function: protein binding; monocarboxylic acid transmembrane transporter activity; taurine transmembrane transporter activity; transmembrane transporter activity
Biological process: monocarboxylic acid transport; organic acid transport; taurine transmembrane transport; transmembrane transport
Cellular component: basolateral plasma membrane; membrane; plasma membrane
Genetic constraint (gnomAD): Loss-of-function variants: 15 observed, 33.24 expected, observed/expected ratio (o/e) 0.45, 90% interval 0.3 to 0.69. The upper end of that interval is the gene's LOEUF score, 0.69, which puts it in group 2 of 6, group 1 being the genes least tolerant of losing a copy. Missense variants: 431 observed, 613.95 expected, observed/expected ratio (o/e) 0.7, 90% interval 0.65 to 0.76. Synonymous variants: 209 observed, 228.6 expected, observed/expected ratio (o/e) 0.91, 90% interval 0.82 to 1.02.
Homologues: Orthologues: chimpanzee SLC16A6 (99% identical), macaque SLC16A6 (98% identical), guinea pig SLC16A6 (87% identical), dog SLC16A6 (86% identical), rabbit SLC16A6 (85% identical), mouse Slc16a6 (85% identical), pig SLC16A6 (84% identical), rat Slc16a6 (82% identical), tropical clawed frog slc16a6 (65% identical), zebrafish slc16a6b (54% identical), zebrafish slc16a6a (50% identical), zebrafish SLC16A6 (50% identical), and 13 more. Paralogues in human: SLC16A7 (28% identical), SLC16A1 (27% identical), SLC16A3 (26% identical), SLC16A13 (26% identical), SLC16A5 (26% identical), SLC16A8 (24% identical), SLC16A12 (24% identical), SLC16A4 (23% identical), SLC16A14 (22% identical), SLC16A9 (22% identical), SLC16A11 (21% identical), SLC16A10 (18% identical), and 1 more.
Diseases named in the same sentence as SLC16A6 in open-access papers:
SLC16A6 is named in the same sentence as 13 diseases in open-access papers, as found by Europe PMC text mining. Sharing a sentence is not in itself a finding about the gene and the disease. The quoted sentences say what the papers report.
breast carcinoma (2 papers, 2013 to 2022). "In breast cancer, the strongest associations included either SNPs in or gene burden scores for genes LDLRAD1, SLC19A1, FGFBP3, CASP5, MMAB, SLC16A6, and INS-IGF2." (PMID 23555315, 2013). "As for SLC16A6, CCL5, and MAL2, their protein expression was almost negative in breast cancer tissues based on the results of the HPA database." (PMID 36341328, 2022).
deafness (2 papers, 2014 to 2017). An inherited or acquired condition characterized by the complete loss of the ability to hear from one or both ears. "Results of previous studies provide evidence that HEY2 regulates the differentiation of mammalian auditory hair cells, whereas SLC16A6 is expressed in cochlear sensory hair cells and plays a role in deafness." (PMID 28097054, 2017).
Hepatic steatosis (2 papers, 2022 to 2025). Steatosis is a term used to denote lipid accumulation within hepatocytes. "Zebrafish Slc16a6a, an ortholog of SLC16A6, transports β-hydroxybutyrate in the liver; Slc16a6a function-loss-mutant has been implicated in hepatic steatosis." (PMID 35257743, 2022). "The phenotype of hepatic steatosis seen in these mutants is reversed when genetically forced to express either wildtype zebra fish Slc16a6 or human SLC16A6, demonstrating the functional similarity between zebra fish and human transporters." (PMID 40305364, 2025).
ovarian carcinoma (2 papers, 2015 to 2016). A malignant neoplasm originating from the surface ovarian epithelium. "SLC16A6 functions as a proton-linked monocarboxylate transporter and was found to be significantly increased in drug resistant ovarian cancer cell lines." (PMID 26573568, 2015). "SLC16A6, a monocaroboxylate transporter, the expression of which has been previously found to be significantly increased in paclitaxel-resistant variant of W1 ovarian cancer cell line." (PMID 27487134, 2016).
steatosis (1 paper, 2022). Increased lipid within the cytoplasm of cells. "Exogenous gene expression of human SLC16A6 in the liver, instead of Slc16a6a, enabled liver recovery from the steatosis." (PMID 35257743, 2022).
type 2 diabetes mellitus (1 paper, 2018). A type of diabetes mellitus that is characterized by insulin resistance or desensitization and increased blood glucose levels. "While all three sites of SLC16A6 function might be important determinants of height, the association of loss-of-function coding variations within the pyruvate transporter SLC16A11 gene and type 2 diabetes mellitus appears to be due to loss of SLC16A11 function in liver exclusively." (PMID 30692937, 2018).
tumor (3 papers, 2023 to 2025). "In this study, we identified and validated three tumor suppressors (SLC16A6, CCR7, and MS4A1) in AML; they were markedly reduced in AML patients." (PMID 41036204, 2025). "Our study identified and validated the efficacy of SLC16A6, CCR7, and MS4A1 as tumor suppressors implicated in AML progression and related to immune cell infiltration." (PMID 41036204, 2025). "Immunohistochemistry (IHC) results from HPA demonstrated that DLGAP5 protein was found to be strongly expressed in BC tumor tissues, while SLC16A6, CAB39L, and HBA demonstrated lower protein expression in BC tissues." (PMID 37142271, 2023). "Notably, the marked activation of CYP1A1, CYP1B1, and SLC16A6, coupled with the downregulation of tumour suppressors such as LINC01085 and CBS, underscores the potential of PM2.5 to promote oxidative stress, carcinogenesis, and therapy resistance in a mutation-dependent manner." (PMID 40559957, 2025). "In conclusion, our study identified and validated CCR7, SLC16A6, and MS4A1 as tumor suppressors involved in the development of AML and related to immune cell infiltration." (PMID 41036204, 2025).
infection (2 papers, 2014 to 2023). The state of being infected such as from the introduction of a foreign agent such as serum, vaccine, antigenic substance or organism. "Many solute carrier (SLC) family genes were also activated at 24 or 48 h after infection, including SLC16A12, SLC2A3, SLC16A6, and SLC32A1." (PMID 37211158, 2023).
cancer (1 paper, 2025). A tumor composed of atypical neoplastic, often pleomorphic cells that invade other tissues. "SLC16A6 expression increased by 1.4-fold in A549 and 2.3-fold in NCI-H1975, indicating that metabolic shifts under PM2.5 stress are more pronounced in EGFR-mutant cancer cells." (PMID 40559957, 2025).
SLC16A6 also shares sentences with these, for which no sentence is quoted: colon cancer (1 paper); cutaneous melanoma (1); endometriosis (1); melanoma (1).